KIF1B (kinesin family member 1B)
Description:
Has a plus-end-directed microtubule motor activity and functions as a motor for transport of vesicles and organelles along microtubules. [Isoform 2]: Has a plus-end-directed microtubule motor activity and functions as a motor for anterograde synaptic vesicle transport along axonal microtubules from the cell body to the presynapse in neuronal cells (By similarity). Functions as a downstream effector in a developmental apoptotic pathway that is activated when nerve growth factor (NGF) becomes limiting for neuronal progenitor cells. [Isoform 3]: Has a plus-end-directed microtubule motor activity and functions as a motor for anterograde transport of mitochondria.
Synonyms: Klp; KIAA0591; HMSNII; CMT2; CMT2A; CMT2A1; NBLST1
Tractability: PROTAC: ubiquitination databases record sites on it; its protein half-life has been measured.
Target class: Other cytosolic protein
Gene: Protein-coding gene on chromosome 1 (10,210,533 to 10,381,606, forward strand). Ensembl gene ENSG00000054523.
Subcellular location: Cytoplasm, cytoskeleton; Cytoplasmic vesicle, secretory vesicle, synaptic vesicle membrane (Isoform 2); Mitochondrion (Isoform 3)
Subcellular location (Human Protein Atlas): End piece; Microtubules; Mid piece; Principal piece
Pathways (Reactome):
Hemostasis: Kinesins
Vesicle-mediated transport: COPI-dependent Golgi-to-ER retrograde traffic
Gene Ontology:
Molecular function: plus-end-directed microtubule motor activity; protein binding; kinesin binding; ATP binding; cytoskeletal motor activity; microtubule binding; microtubule motor activity
Biological process: anterograde synaptic vesicle transport; neuromuscular synaptic transmission; neuron-neuron synaptic transmission; retrograde neuronal dense core vesicle transport; vesicle-mediated transport; microtubule-based movement; transport along microtubule
Cellular component: mitochondrion; axon; cytoplasmic vesicle; dendrite; kinesin complex; neuron projection; synaptic vesicle membrane; axon cytoplasm; cytoskeleton; postsynapse; presynapse
Genetic constraint (gnomAD): Loss-of-function variants: 57 observed, 189.12 expected, observed/expected ratio (o/e) 0.3, 90% interval 0.24 to 0.38. The upper end of that interval is the gene's LOEUF score, 0.38, which puts it in group 1 of 6, group 1 being the genes least tolerant of losing a copy. Missense variants: 1,451 observed, 2,112.9 expected, observed/expected ratio (o/e) 0.69, 90% interval 0.66 to 0.72. Synonymous variants: 670 observed, 757.43 expected, observed/expected ratio (o/e) 0.88, 90% interval 0.83 to 0.94.
Gene-disease validity (ClinGen):
ClinGen rates the evidence that KIF1B causes each of these diseases.
Charcot-Marie-Tooth disease type 2A1 (autosomal dominant): Limited. Autosomal dominant Charcot-Marie-Tooth disease type 2A1 (CMT2A1) is a form of axonal Charcot-Marie-Tooth disease, a peripheral sensorimotor neuropathy.
Homologues: Orthologues: macaque KIF1B (99% identical), chimpanzee KIF1B (99% identical), pig KIF1B (98% identical), dog KIF1B (98% identical), rabbit KIF1B (98% identical), mouse Kif1b (97% identical), rat Kif1b (97% identical), guinea pig KIF1B (95% identical), zebrafish kif1b (85% identical), tropical clawed frog kif1b (83% identical). Paralogues in human: KIF1A (70% identical), KIF1C (33% identical), KIF13B (27% identical), KIF13A (27% identical), KIF16B (21% identical), KIF14 (20% identical), KIF21B (15% identical), KIF21A (15% identical), CENPE (14% identical), KIF7 (13% identical), KIF17 (13% identical), KIF4B (13% identical), and 29 more.
Diseases named in the same sentence as KIF1B in open-access papers:
KIF1B is named in the same sentence as 76 diseases in open-access papers, as found by Europe PMC text mining. Sharing a sentence is not in itself a finding about the gene and the disease. The quoted sentences say what the papers report.
neuroblastoma (14 papers, 2012 to 2025). Neuroblastoma (NB) is the most common solid, extracranial childhood tumor. "Chromosome 1p36.22 candidate gene KIF1B is a tumor suppressor gene in neuroblastoma and germline KIF1B deletion is associated with high predisposition of neuroblastoma development." (PMID 37904225, 2023). "Overexpression of KIF1B in neuroblastoma cell lines causes apoptotic cell death and its knockdown enhances tumor formation in mouse models." (PMID 35246212, 2022). "Later, a group of relatives was found that increased probability of developing not only PCC, but also neuroblastomas, ganglioneuromas, and lung tumors for germline mutations in the KIF1B gene." (PMID 29504908, 2018). "To illustrate the utility of comparing normal and tumor tissues, we examined ASE for a well-established imprinted gene, H19, and for a tumor suppressor gene, KIF1B, which is located on chromosome 1p and is frequently deleted in neuroblastoma." (PMID 35246212, 2022). "As expected, H19 has very strong ASE in almost all normal and tumor samples, whereas ASE of KIF1B is observed exclusively in neuroblastoma samples." (PMID 35246212, 2022). "The prognostic effects of age related genes ALCAM, CACNA2D3, DST, EPB41L4A and KIF1B in pediatric neuroblastoma patients were determined by Kaplan-Meier survival." (PMID 34116676, 2021). "Conversely enforced expression of KIF1B resulted in an induction of apoptosis of neuroblastoma (NB) cells." (PMID 33112832, 2020). "We found that ALCAM, CACNA2D3, DST, EPB41L4A and KIF1B were associated with the favorable prognosis of MYCN non-amplified neuroblastoma patients." (PMID 34116676, 2021). "And the higher expression levels of ALCAM, CACNA2D3, DST, EPB41L4A or KIF1B were associated with better prognosis of MYCN non-amplified neuroblastoma patients." (PMID 34116676, 2021). "Next, we tried to determine the associations of ALCAM, CACNA2D3, DST, EPB41L4A and KIF1B in MYCN non-amplified neuroblastoma patients." (PMID 34116676, 2021). "KIF1B functions as a tumour suppressor in neuroblastoma, but promotes GC invasion." (PMID 32939931, 2020). "While KIF1B was found to be the second most frequently mutated gene in a multicentric Belgian PPGL patient cohort, the T827I mutation in exon 24 of the KIF1Bβ-isoform has hitherto only previously been described in a paraganglioma and a neuroblastoma." (PMID 33138083, 2020). "KIF1B gene resides on chromosome 1p36.2, a region frequently deleted in neuroblastomas." (PMID 27097110, 2016). "In addition, KIF1B has been reported to have a haploinsufficient tumor-suppressor function in primary neuroblastomas and pheochromocytomas by acting downstream from EglN3 prolyl hydroxylase." (PMID 23028799, 2012). "In this family, the heritability of PCC is linked to the MAX germline variant and not to the KIF1B germline variant which, however, may have contributed to the occurrence of neuroblastoma (NB) in the proband." (PMID 33112832, 2020). "In the Neuroblastoma case, there are seven conflicting interpretations (KIF1:c.3787 C>T, KIF1B:c.2618C>T, ALK:c.3749T>C, ALK:c.3452C>T, ALK:c.3575G>C, ALK:3383G>C, and ALK:c.3824G>A)." (PMID 37946154, 2023). "Neuroblastoma patients with higher expression levels of ALCAM, CACNA2D3, DST, EPB41L4A or KIF1B had better clinical overall survival in TARGET dataset, GSE49710 dataset and GSE85047 dataset." (PMID 34116676, 2021). "Kinesin Family Member 1B (KIF1B) is a tumor suppressor in many cancers, including those of liver, colon, breast, and brain (aggressive neuroblastoma), and pheochromocytoma." (PMID 30947687, 2019). "ALCAM, CACNA2D3, DST, EPB41L4A and KIF1B were highly expressed in MYCN non-amplified younger neuroblastoma patients." (PMID 34116676, 2021). "However, a large number of genes located within the 1p36 region have been proposed as tumor suppressors in neuroblastoma and other tumors, including CHD5, CAMTA1, miRNA-34a, CASZ1, KIF1B, and the HES gene family." (PMID 27014418, 2016).
neuroblastoma (continued). "Interestingly, high expression levels of ALCAM, CACNA2D3, DST, EPB41L4A or KIF1B were not only associated with the prognosis of MYCN non-amplified neuroblastoma patients, but also were associated with the prognosis of all neuroblastoma patients." (PMID 34116676, 2021). "Furthermore, using multivariate cox regression, we determined the correlations of age, ALCAM, CACNA2D3, DST, EPB41L4A or KIF1B expression in the prediction of the clinical overall survival of MYCN non-amplified neuroblastoma patients." (PMID 34116676, 2021). "Moreover, the prognostic significances of ALCAM, CACNA2D3, EPB41L4A and KIF1B in MYCN non-amplified pediatric neuroblastoma were not previously reported." (PMID 34116676, 2021). "MYCN non-amplified neuroblastoma patients with lower expression levels of ALCAM, CACNA2D3, DST, EPB41L4A or KIF1B were with lower overall survival in TARGET dataset, GSE49710 dataset and GSE85047 dataset." (PMID 34116676, 2021). "MYCN non-amplified neuroblastoma is a heterogeneous disease and could be divided into sub-groups based on age or the expression levels of ALCAM, CACNA2D3, DST, EPB41L4A and KIF1B." (PMID 34116676, 2021).
pheochromocytoma (11 papers, 2012 to 2025). "Both germline and somatic mutations in KIF1B gene have been found in pheochromocytoma, occasionally occurring in combinations with mutations in other genes, such as NF1, RET, VHL, and SDHx." (PMID 29504908, 2018). "Missense mutations in the KIF1B gene were first detected in two samples of pheochromocytoma in 2008." (PMID 28187001, 2017). "In addition, a kinesin family member 1B (KIF1B) missense mutation in pheochromocytomas has been identified." (PMID 40149362, 2025). "KIF1B is a rare reason for pheochromocytoma and TMEM127 is a susceptibility gene for PGL/PCC." (PMID 33777662, 2021). "Cluster 2 PPGLs are built-up mostly by pheochromocytomas driven by variants in genes regulating kinase-driven pathways, including NF1, KIF1B, MAX, RET, TMEM127 and H-RAS." (PMID 35205664, 2022). "More recently, the TMEM127, MAX, HIF2A, EGLN1, KIF1B, and H-RAS complete the list of susceptibility genes implicated in the development of paragangliomas/pheochromocytomas." (PMID 24899893, 2014). "In another study, a group of relatives was found who carried germline mutations in the KIF1B gene and showed an increased probability of developing not only pheochromocytomas but also neuroblastomas, ganglioneuromas, and lung tumors." (PMID 28187001, 2017).
hepatocellular carcinoma (10 papers, 2012 to 2021). A malignant tumor that arises from hepatocytes. "Recently, a genome-wide association study demonstrated an association between polymorphisms in the KIF1B gene and the risk of hepatocellular carcinoma (HCC)." (PMID 34112167, 2021). "Recently, a genome-wide association study revealed an association between polymorphisms in the KIF1B gene and the risk of hepatocellular carcinoma (HCC), and several case-control studies have further investigated this relationship." (PMID 23634229, 2013). "Genome-wide association studies (GWAS) have recently identified KIF1B as susceptibility locus for hepatitis B virus (HBV)–related hepatocellular carcinoma (HCC)." (PMID 22807686, 2012). "A recent genome wide association study (GWAS) study conducted on a Chinese population has reported the involvement of a KIF1B genetic variant in Hepatitis B virus (HBV)-related hepatocellular carcinoma (HCC)." (PMID 23028799, 2012). "Although two meta-analyses on the associations between KIF1B rs17401966 polymorphism and hepatocellular carcinoma and one meta-analyses on the associations between KIF1B rs17401966 polymorphism and HBV-related hepatocellular carcinoma have been reported in the last 5 years." (PMID 30947687, 2019). "Another study documented that downregulation of KIF1B mRNA in hepatocellular carcinoma tissues correlates with poor prognosis." (PMID 34112167, 2021). "Several studies have focused on the association between KIF1B rs17401966 polymorphism and susceptibility to hepatitis B virus-related (HBV-related) hepatocellular carcinoma (HCC), but the conclusions have been inconsistent." (PMID 30947687, 2019). "A recent genome-wide association study (GWAS) using chronic HBV (hepatitis B virus) carriers with and without hepatocellular carcinoma (HCC) in five independent Chinese populations found that one SNP (rs17401966) in KIF1B was associated with susceptibility to HCC." (PMID 22712471, 2012). "Finally, the leiomyosarcoma and hepatic carcinoma of the proband, and her father’s lung adenocarcinoma may be MAX and KIF1B independent." (PMID 33112832, 2020).
paraganglioma (9 papers, 2014 to 2025). A benign or malignant neoplasm arising from paraganglia located along the sympathetic or parasympathetic nerves. "This case reported rare co-occurring variants in SDHB and KIF1B and unusual imaging findings of metastasis in paraganglioma." (PMID 40917352, 2025). "Recently, other genes (TMEM127, MAX, HIF2A, EGLN1, KIF1B, H-RAS) have been added to the group of susceptibility genes involved in the development of paragangliomas/PHEO." (PMID 26084817, 2015). "No record of paraganglioma with a mutation in the KIF1B gene has been published." (PMID 28187001, 2017). "Notably, this case identified rare co-occurring variants, an SDHB pathogenic variant and a KIF1B VUS, underscoring the critical need for comprehensive germline and somatic genetic testing in such cases, offering valuable insights and data for the diagnosis, management, and research of paraganglioma." (PMID 40917352, 2025).
Charcot-Marie-Tooth disease (5 papers, 2017 to 2025). An inherited degenerative disorder involving the peripheral nerves. "Consistently, mutations in the motor domain of Kif1b were found in one of the motor and sensory neuropathies, Charcot-Marie-Tooth disease." (PMID 30590745, 2019). "The KIF1B gene encodes a motor protein that transports mitochondria and synaptic vesicle precursors and mutations in this gene have been associated with Charcot-Marie-Tooth disease." (PMID 28968953, 2017). "KIF1B is another interesting gene involved in Charcot-Marie-Tooth disease, which is characterized by distal limb muscle weakness and atrophy due to peripheral neuropathy." (PMID 29691431, 2018). "She carried the c.5225T>A, p.Leu1752Gln heterozygous variant in thekinesin family member 1B (KIF1B) gene (OMIM#118210, phenotype:Charcot-Marie-Tooth disease (CMT), autosomal dominant)." (PMID 41504202, 2025).
Charcot-Marie-Tooth disease type 2A (4 papers, 2013 to 2024). "Charcot-Marie-Tooth disease type 2A can be caused by mutations in Kif1b, congenital fibrosis of the extraocular muscles can be caused by mutations in Kif21a, and a loss-of-function mutation in Kif5a motor domain can result in hereditary spastic paraplegia." (PMID 35259089, 2022). "Mutations in human KIF1B cause Charcot-Marie-Tooth disease type 2A and have been linked to multiple sclerosis." (PMID 23342162, 2013). "Furthermore, variants in KIF1B are documented as causing autosomal dominant inherited disorders including Charcot-Marie Tooth Disease type 2A1 (MIM# 118,210) and pheocychromatoma (MIM# 171,300)." (PMID 35699875, 2022). "Lastly, the phenotype associated with pathogenic variants of KIF1B, peripheral sensorimotor neuropathy named Charcot-Marie-Tooth disease type 2A1 (MIM: 118210), is highly dissimilar to speech delay; therefore, the variant in this gene was also classified as a variant of unknown significance." (PMID 40225914, 2024).
multiple sclerosis (4 papers, 2013 to 2021). A progressive autoimmune disorder affecting the central nervous system resulting in demyelination. "Another example is kinesin family member 1B (kif1b), which has been associated with susceptibility to multiple sclerosis." (PMID 29764394, 2018). "Moreover, KIF1B has been associated with susceptibility of multiple sclerosis." (PMID 32033476, 2020). "KIF5A along with other kinesin members including KIF1B and KIF21B were significantly reduced at the mRNA level and KIF5A at the protein level in gray matter of multiple sclerosis (MS) brains." (PMID 33691783, 2021).
ovarian carcinoma (4 papers, 2020 to 2024). A malignant neoplasm originating from the surface ovarian epithelium. "The top 10 genes with most deleterious mutations in the Chinese ovarian cancer population were MC1R (12%), MLH1 (9%), PRKDC (8%), KIF1B (8%), FANCM (7%), FANCI (6%), PRSS1 (6%), SDHA (6%), BRCA2 (6%), and CFTR (5%)." (PMID 38817903, 2024). "Knockdown of RBFOX2 significantly upregulation of the KIF1B and increased sensitivity to anoikis in ovarian cancer cells." (PMID 38881877, 2024). "By sponging miR-211, MALAT1 up-regulates PHF19 expression and induces RBFOX2 expression and alternative processing of the tumor suppressor gene KIF1B, leading to ovarian cancer cell proliferation, invasion, increased anoikis, and anchorage-independent growth." (PMID 32174966, 2020). "Furthermore, the high-frequency mutated genes in the American population fell within the screening range recommended by the NCCN guidelines, while the high-frequency mutated genes, MC1R, PRKDC, and KIF1B in the Chinese ovarian cancer cohort were not covered." (PMID 38817903, 2024). "AS events of KIF1B and CLSTN1 have been reported to be involved in ovarian cancer and lung cancer development." (PMID 32939931, 2020).
Sepsis (4 papers, 2019 to 2023). Sepsis is defined as life-threatening organ dysfunction caused by a dysregulated host response to infection. "In a study aiming to identify sepsis in children based on machine learning, the authors identified KIF1B as a pivotal gene using LASSO and RF algorithms." (PMID 37834169, 2023). "Among them, the AUCs of ITGAM, KIF1B, RRAGD, S100A9, SCOC, and SPTLC2 in the internal and external test sets were more than 0.6, indicating diagnostic significance for sepsis." (PMID 37834169, 2023).
neuropathy (3 papers, 2020 to 2025). A disorder affecting the nervous system that manifests with pain, tingling, numbness, and/or muscle weakness. "On the contrary, a heterozygous missense variant in KIF1B was proposed to cause neuropathy by impairing insulin‐like growth factor 1 receptor (IGF1R) in a recent study." (PMID 39776111, 2025). "Kif1b has been revealed mutated in the neuropathy Charcot–Marie–Tooth disease type 2A and reduced retinal expression of Kif1b mediated retinal ganglion cell decline in a mouse model of chronic glaucoma." (PMID 32341448, 2020).
epilepsy (2 papers, 2013 to 2021). A brain disorder characterized by episodes of abnormally increased neuronal discharge resulting in transient episodes of sensory or motor neurological dysfunction, or psychic dysfunction. "Thus, it is possible that deregulation of GAA, KIF1B and SNCA is involved in pathology of human PAX6 patients with a range of neurological disorders including autism, cognitive disorders, epilepsy and mental retardation." (PMID 23342162, 2013).
glioma (2 papers, 2023 to 2025). A benign or malignant brain and spinal cord tumor that arises from glial cells (astrocytes, oligodendrocytes, ependymal cells). "Additionally, circ0030018 is overexpressed in glioma and promotes glioma tumorigenesis through the miR‐185–5p/KIF1B signaling." (PMID 37250146, 2023).
neural tumors (2 papers, 2013 to 2021). "Frequent deletions of the kinesin-like protein gene 1B (KIF1B) have been reported in neural tumors." (PMID 23634229, 2013).